AIFM1 (apoptosis inducing factor mitochondria associated 1)
Description:
Functions both as NADH oxidoreductase and as regulator of apoptosis. In response to apoptotic stimuli, it is released from the mitochondrion intermembrane space into the cytosol and to the nucleus, where it functions as a proapoptotic factor in a caspase-independent pathway. Release into the cytoplasm is mediated upon binding to poly-ADP-ribose chains (By similarity). The soluble form (AIFsol) found in the nucleus induces 'parthanatos' i.e. caspase-independent fragmentation of chromosomal DNA. Binds to DNA in a sequence-independent manner. Interacts with EIF3G, and thereby inhibits the EIF3 machinery and protein synthesis, and activates caspase-7 to amplify apoptosis. Plays a critical role in caspase-independent, pyknotic cell death in hydrogen peroxide-exposed cells. In contrast, participates in normal mitochondrial metabolism. Plays an important role in the regulation of respiratory chain biogenesis by interacting with CHCHD4 and controlling CHCHD4 mitochondrial import. [Isoform 4]: Has NADH oxidoreductase activity. Does not induce nuclear apoptosis. [Isoform 5]: Pro-apoptotic isoform.
Synonyms: AIF; PDCD8; CMTX4; DFNX5; AUNX1; CMT2D; COWCK; COXPD6; NADMR; NAMSD; SEMDHL
Tractability: Small molecule: a structure with a bound ligand is known; it has a high-quality binding pocket. PROTAC: UniProt records ubiquitination sites on it; ubiquitination databases record sites on it; its protein half-life has been measured.
Target class: Enzyme; Oxidoreductase
Gene: Protein-coding gene on chromosome X (130,124,666 to 130,165,879, reverse strand). Ensembl gene ENSG00000156709.
Subcellular location: Mitochondrion intermembrane space; Mitochondrion inner membrane; Cytoplasm; Nucleus; Cytoplasm, perinuclear region; Mitochondrion intermembrane space (Isoform 3); Mitochondrion (Isoform 4); Cytoplasm, cytosol; Cytoplasm (Isoform 5)
Subcellular location (Human Protein Atlas): Mitochondria; Connecting piece
Gene Ontology:
Molecular function: DNA binding; FAD binding; NAD(P)H oxidase H2O2-forming activity; NADH binding; NADH dehydrogenase activity; oxidoreductase activity, acting on NAD(P)H; protein binding; protein-membrane adaptor activity; poly-ADP-D-ribose binding; oxidoreductase activity; protein dimerization activity
Biological process: apoptotic process; mitochondrial disulfide relay system; mitochondrial respiratory chain complex assembly; positive regulation of apoptotic process; protein import into mitochondrial intermembrane space; intrinsic apoptotic signaling pathway in response to endoplasmic reticulum stress; positive regulation of necroptotic process; cellular response to aldosterone; cellular response to estradiol stimulus; cellular response to hydrogen peroxide; cellular response to hypoxia; cellular response to nitric oxide; positive regulation of neuron apoptotic process; positive regulation of programmed cell death; response to ischemia; response to L-glutamate; response to toxic substance
Cellular component: cytoplasm; mitochondrial inner membrane; mitochondrial intermembrane space; mitochondrion; nucleus; cytosol; perinuclear region of cytoplasm
Gene-disease validity (ClinGen):
ClinGen rates the evidence that AIFM1 causes each of these diseases.
X-linked hereditary sensory and autonomic neuropathy with hearing loss (X-linked): Definitive. This syndrome is characterized by the association of an axonal sensory and autonomic neuropathy with hearing loss.
Leigh syndrome (X-linked): Moderate. A progressive neurological disease defined by specific neuropathological features associating brainstem and basal ganglia lesions.
Homologues: Orthologues: macaque AIFM1 (99% identical), rabbit AIFM1 (96% identical), guinea pig AIFM1 (94% identical), dog AIFM1 (94% identical), rat Aifm1 (92% identical), pig AIFM1 (90% identical), chimpanzee AIFM1 (89% identical), mouse Aifm1 (88% identical), zebrafish aifm1 (70% identical), tropical clawed frog aifm1 (66% identical), Drosophila melanogaster AIF (45% identical), Caenorhabditis elegans wah-1 (33% identical). Paralogues in human: TXNRD1 (18% identical), TXNRD3 (17% identical), AIFM3 (17% identical), TXNRD2 (16% identical), GSR (15% identical), DLD (14% identical), PYROXD1 (13% identical).
Diseases named in the same sentence as AIFM1 in open-access papers:
AIFM1 is named in the same sentence as 161 diseases in open-access papers, as found by Europe PMC text mining. Sharing a sentence is not in itself a finding about the gene and the disease. The quoted sentences say what the papers report.
Cowchock syndrome (13 papers, 2015 to 2024). "Mutations in the AIFM1 gene cause neuropathy and are associated with Cowchock syndrome, a neuromuscular disorder associated with sensorineural hearing loss." (PMID 39442262, 2024). "Our study is consistent with previous studies showing that variants in AIFM1 lead to Cowchock syndrome." (PMID 37173762, 2023). "Mutations in the AIFM1 gene cause neuropathy and are associated with Cowchock syndrome, a neuromuscular disorder associated with deafness and cognitive impairment." (PMID 36529647, 2022). "In a study of AIFM1 mutation causing Cowchock Syndrome, the mutant AIFM1 showed more AIFM1-positive inclusions detected by immunofluorescence, indicating a higher propensity to translocate to the nucleus." (PMID 36479253, 2022). "In humans, AIFM1 mutations have been identified in patients suffering from severe X-linked mitochondrial encephalomyopathy and Cowchock syndrome, both conditions affecting the nervous system and skeletal muscle." (PMID 33367954, 2021). "Diseases caused by AIFM1 gene mutations have previously been described as progressive mitochondrial encephalomyopathy (c.601_603delAGA, p.Arg201 deletion), Cowchock syndrome (c.1478A>T, p.Glu493Val missense mutation) or auditory neuropathy (c.1288C>T, p.Arg430Cys missense mutation)." (PMID 31188924, 2019). "AIFM1 (OMIM: 300169) has been associated with X-linked deafness-5 with peripheral neuropathy (DFNX5, OMIM: 300614), Cowchock syndrome (OMIM: 300169), and combined oxidative phosphorylation deficiency 6 (OMIM: 300816)." (PMID 39767564, 2024). "AIFM1 mutation can contribute to several primary X-linked pathologies, two of which include: (i) combined oxidative phosphorylation deficiency 6 (COXPD6, MIM #300816) and (ii) Cowchock syndrome (CMTX4, MIM #310490)." (PMID 36475414, 2022). "This difference was probably due to the fact that AIFM1 could cause a variety of diseases, such as childhood cerebellar ataxia, mitochondrial encephalomyopathy, motor neuropathy, Cowchock syndrome and auditory neuropathy, with different severity and potential pathogenesis." (PMID 36479253, 2022). "AIFM1 is the most common gene in our non-infant subgroup, and pathogenic variants in AIFM1 have also been identified in cases with combined oxidative phosphorylation deficiency 6, Cowchock syndrome, and spondyloepimetaphyseal dysplasia." (PMID 38456936, 2024). "The apoptosis-inducing factor mitochondria associated-1 (AIFM1) is the main pathogenic gene of the X-linked recessive Charcot-Marie-Tooth disease-4 with or without cerebellar ataxia (CMTX4), also known as Cowchock syndrome." (PMID 37173762, 2023).
breast carcinoma (10 papers, 2012 to 2025). "PARP1 is significantly amplified and highly expressed in recurrent breast cancer, while PTEN loss has been linked to an increased risk of breast cancer, and AIFM1 plays a crucial role in tumor invasion and metastasis by inactivating PTEN." (PMID 40564403, 2025). "Key genes in the parthanatos pathway, such as PARP1, PTEN, and AIFM1, are critical drivers of breast cancer initiation, progression, drug resistance, and metastasis." (PMID 40564403, 2025). "Moreover, in the case of control samples, we found overexpression of the proteins: PRDX2, PRDX5 and AIFM1 involved in ROS; TUSC2 in PMM; ALKBH7, RHOT1, SAMM50, IMMT and HSPA9 in the MMO; and FUNDC2 in MIT compared to luminal A and basal-like breast cancer tumors." (PMID 35327574, 2022).
hearing loss (10 papers, 2015 to 2025). "The molecular disease-causing mechanism of AIFM1 mutation-related hearing loss is still unclear; the mitochondrial function and the caspase-independent apoptosis to neuronal development and adult neurogenesis play a critical role in previous studies." (PMID 32684920, 2020). "AIFM1 mutations have previously been associated with neurologic presentations as varied as intellectual disability, hearing loss, neuropathy, and striatal necrosis, while AIFM1 mutations in this small region present with a distinct phenotype implicating bone." (PMID 28842795, 2017). "Variants in AIFM1 have been shown to be associated with diverse neurological disorders featuring intellectual disability, sensory hearing loss, neuropathy, and an encephalopathy associated with striatal abnormalities on neuroimaging." (PMID 28842795, 2017). "Therefore, we considered that this novel missense variant in AIFM1 was pathogenic and responsible for the X-linked recessive hearing loss in this pedigree." (PMID 31188924, 2019). "For what concerns X-linked non-syndromic hearing loss, 5 genes have been identified so far: PRPS1, SMPX, AIFM1, COL4A6, and POU3F4." (PMID 37371790, 2023). "Mutations in the AIFM1 (apoptosis-inducing factor mitochondrion-associated 1) gene, which encodes a flavin adenine dinucleotide-containing, NADH-dependent oxidoreductase resides in the mitochondrial intermembrane space, can cause either non-syndromic or syndromic hearing loss." (PMID 31188924, 2019).
colorectal cancer (9 papers, 2016 to 2025). A primary or metastatic malignant neoplasm that affects the colon or rectum. "A study indicated that AIFM1 is a core gene in ulcerative colitis‐associated colorectal cancer." (PMID 40837128, 2025). "This pathway exhibits context-dependent duality: pro-death in colorectal cancer via Auriculasin-enhanced KEAP1/AIFM1 signaling versus pro-survival upon KEAP1/AIFM1 inhibition." (PMID 40741332, 2025).
auditory neuropathy (8 papers, 2015 to 2023). A hearing disorder characterized by impaired transmission of signals through the auditory nerve, resulting in mild to severe hearing loss and poor speech perception. "In conclusion, our study identifies AIFM1 as a new causal gene associated with X-linked auditory neuropathy and delayed peripheral neuropathy." (PMID 25986071, 2015).
melanoma (8 papers, 2012 to 2023). A malignant, usually aggressive tumor composed of atypical, neoplastic melanocytes. "However, the relevance of AIFM1 in melanoma remains uncertain." (PMID 37147395, 2023).
deafness (7 papers, 2018 to 2024). An inherited or acquired condition characterized by the complete loss of the ability to hear from one or both ears. "It is rare, and to date, there are few reports of AIFM1 mutations causing deafness." (PMID 39442262, 2024). "It is rare, and to date, there are only 11 reports of AIFM1 mutations causing deafness." (PMID 36529647, 2022). "X-linked hemizygous mutations in AIFM1, which encodes apoptosis-inducible factor (AIF) a binder of free PAR, are causative for Charcot–Marie–Tooth disease type 4 in combination with deafness and cognitive impairment." (PMID 34479984, 2021). "Gene therapy may provide possibility for the treatment of AIFM1-related AN, but the approach does not be explored in X-linked deafness-related genes." (PMID 39272213, 2024).
ischemia (6 papers, 2013 to 2024). A hypoperfusion of the BLOOD through an organ or tissue caused by a PATHOLOGIC CONSTRICTION or obstruction of its BLOOD VESSELS, or an absence of BLOOD CIRCULATION. "This means that NSC simultaneously down-regulate Aifm1 and up-regulate Iduna, which is a combination with a possibly enormous protective effect on ischemia-affected tissue." (PMID 30394012, 2018).
Cognitive impairment (5 papers, 2021 to 2025). Abnormal cognition is characterized by deficits in thinking, reasoning, or remembering. "We previously hypothesized a role of IgG against DAB1, AIFM1, and SURF1 in cognitive impairment in COVID-19, given the well-described functions of the three proteins in neurogenesis and synaptic plasticity." (PMID 40995367, 2025).
Ataxia (4 papers, 2021 to 2025). Ataxia refers to impaired coordination of voluntary muscle movement. "As for other metabolic disorders associated with aberrant mitochondrial bioenergetics, pathogenic AIFM1 mutations cause a large spectrum of clinical outcomes, including fatal encephalomyopathy, ataxia, late-onset neuromyopathy, and mild deafness." (PMID 41326385, 2025). "It has been reported that prolonged treatment with riboflavin may result in some mild improvement in the ataxia caused by AIFM1 mutation." (PMID 39767564, 2024).
encephalomyopathy (4 papers, 2018 to 2025). "Mitochondrial disease arising from defects in mitochondrial apoptosis inducing factor 1 (AIFM1) can cause a wide range of symptoms including encephalomyopathy, cerebellar ataxia, peripheral neuropathy, etc.." (PMID 36056365, 2022). "Mutations in AIFM-1 are related to fatal encephalomyopathy in infants." (PMID 30050539, 2018).
Intellectual disability (4 papers, 2017 to 2024). "Erk2, as mGluR5, might be another factor underlying human psychiatric disorders; interestingly, patients harboring deleterious AIFM1 mutations often suffer from mental retardation or intellectual disability." (PMID 38796706, 2024). "There was also overlap for genes involved in intellectual disabilities, including AFF2, AIFM1, CA8, EEF1A2, MLC1, and XYLT1, but statistically the overlap is not significant." (PMID 32393163, 2020).
mitochondrial encephalomyopathy (4 papers, 2015 to 2022). A heterogenous group of disorders characterized by alterations of mitochondrial metabolism that result in muscle and nervous system dysfunction. "Previous studies showed that the AIFM1 R201del variant caused severe mitochondrial encephalomyopathy and significantly increased parthanatos-linked cell death." (PMID 36479253, 2022). "The first deleterious mutation in the AIFM1 gene was found in two consanguineous infant males, showing progressive mitochondrial encephalomyopathy." (PMID 32722651, 2020). "Furthermore, in a study of mitochondrial encephalomyopathy caused by R201 del variant in AIFM1, the protein expression was not significantly altered." (PMID 36479253, 2022).
neuropathy (4 papers, 2017 to 2024). A disorder affecting the nervous system that manifests with pain, tingling, numbness, and/or muscle weakness. "TIMM8A and AIFM1 mutation has been identified as potential factors contributing to the development of postsynaptic neuropathy." (PMID 38027523, 2023).
cardiomyopathy (3 papers, 2011 to 2023). A disease of the heart muscle or myocardium proper. "Mutations in the AIFM1 gene led to early prenatal ventriculomegaly and childhood cardiomyopathy; Muscle-specific loss of AIF in mouse led to severe DCM; Harlequin (Hq) mice with AIF deficiency displayed more severe ischemic damage than wild-type hearts." (PMID 34651031, 2021). "Mutations of the AIF-encoding gene AIFM1 led to early prenatal ventriculomegaly and childhood cardiomyopathy, accompanied by respiratory chain complex I and IV deficiency." (PMID 34651031, 2021). "Three out of the 34 OXPHOS genes that did not demonstrate cardiomyopathy in humans did demonstrate cardiomyopathy in mice (Ndufa13, Bcs1l, Aifm1)." (PMID 37103033, 2023).
hepatoma (3 papers, 2013 to 2025). "A recent study has uncovered a new role of AIFM1 on the proliferation of hepatoma cells and cell cycle arrest." (PMID 33805806, 2021).
leukemia (3 papers, 2012 to 2024). A malignant (clonal) hematologic disorder, involving hematopoietic stem cells and characterized by the presence of primitive or atypical myeloid or lymphoid cells in the bone marrow and the blood. "Harlequin mice harbor a 9-kb insertion of the ecotropic leukemia provirus in the first intron of the X-linked apoptosis-inducing factor gene (Aifm1) resulting in an 80%–90% reduction of the corresponding protein (apoptosis-inducing factor [AIF]) abundance in all the tissues." (PMID 38796706, 2024).
spondyloepimetaphyseal dysplasia (3 papers, 2023 to 2024). An osteochondrodysplasia that results in abnormalities of bone growth in the vertebral column, epiphysis, and metaphysis. "A peculiar combination of central hypomyelination and spondyloepimetaphyseal dysplasia (H‐SMD) constitutes a specific phenotype that only partially overlaps with other AIFM1 cases." (PMID 37644805, 2023). "In spondyloepimetaphyseal dysplasia (SEMD) with mental retardation (MR), WES has identified a variant (p.Asp237Gly) in the AIFM1 gene." (PMID 39523358, 2024).
Stroke (3 papers, 2017 to 2021). Sudden impairment of blood flow to a part of the brain due to occlusion or rupture of an artery to the brain. "Aifm1 level in the ipsilateral hemisphere was significantly increased by stroke (P < 0.001) and significantly reduced by NSC transplantation (P < 0.001)." (PMID 30394012, 2018). "In the contralateral hemisphere, Aifm1 level was not increased by stroke, but was significantly reduced by NSC transplantation (P < 0.001), when compared to both healthy and stroke-affected group." (PMID 30394012, 2018).
acute kidney injury (2 papers, 2020 to 2022). Sudden and sustained deterioration of the kidney function characterized by decreased glomerular filtration rate, increased serum creatinine or oliguria. "A recent study showed that a long noncoding RNA, TCONS_00016233 drives sepsis-induced acute kidney injury by targeting miR-22-3p/AIFM1 pathway." (PMID 32412059, 2020).
axonal neuropathy (2 papers, 2018 to 2021). Any nerve disorder affecting the axon of a nerve. "AIFM1, which is required for mitochondrial targeting of Mia40, and thus indirectly of CHCHD10, has been linked to mitochondrial encephalopathy and axonal neuropathy." (PMID 29789341, 2018).
breast tumors (2 papers, 2012 to 2023). "Therefore, we analysed the expression of 6 genes from the OXPHOS signature (AIFM1, NDUFV1, NDUFAB1, NDUFA7, NDUFS6 and MRPS12) among the most enriched in metastatic samples, by RT-PCR in specimens of 503 breast tumours patients with a follow-up of 20 years." (PMID 37452026, 2023).
intervertebral disc degeneration (2 papers, 2023 to 2025). "In the context of intervertebral disc degeneration, SIRT5 protects mitochondrial homeostasis via the desuccinylation modification of AIFM1." (PMID 40243486, 2025).
Mitochondrial encephalopathy (2 papers, 2018 to 2023). "Pathogenic variants in AIFM1 have been associated with a wide spectrum of disorders, spanning from CMT4X to mitochondrial encephalopathy." (PMID 37644805, 2023).